DUSP28 (dual specificity phosphatase 28)
Description:
Has phosphatase activity with the synthetic substrate 6,8-difluoro-4-methylumbelliferyl phosphate (in vitro). Has almost no detectable activity with phosphotyrosine, even less activity with phosphothreonine and displays complete lack of activity with phosphoserine. The poor activity with phosphotyrosine may be due to steric hindrance by bulky amino acid sidechains that obstruct access to the active site.
Synonyms: VHP; DUSP26
Tractability: No criterion of Open Targets' tractability assessment is met for any kind of drug.
Gene: Protein-coding gene on chromosome 2 (240,560,054 to 240,565,256, forward strand). Ensembl gene ENSG00000188542.
Subcellular location (Human Protein Atlas): Nuclear speckles; Cytosol
Gene Ontology:
Molecular function: phosphatase activity; protein serine/threonine phosphatase activity; protein tyrosine phosphatase activity
Biological process: dephosphorylation
Genetic constraint (gnomAD): Loss-of-function variants: 12 observed, 5.02 expected, observed/expected ratio (o/e) 2.39. That is too few expected variants to judge how well the gene tolerates losing a copy. Missense variants: 373 observed, 206.53 expected, observed/expected ratio (o/e) 1.81, 90% interval 1.66 to 1.95. Synonymous variants: 178 observed, 98.25 expected, observed/expected ratio (o/e) 1.81, 90% interval 1.6 to 1.97.
Homologues: Orthologues: chimpanzee DUSP28 (99% identical), macaque DUSP28 (94% identical), pig DUSP28 (82% identical), guinea pig DUSP28 (80% identical), mouse Dusp28 (74% identical), rat Dusp28 (73% identical), zebrafish dusp28 (42% identical), tropical clawed frog dusp28 (31% identical). Paralogues in human: SSH1 (34% identical), SSH3 (34% identical), SSH2 (31% identical), DUSP15 (31% identical), DUSP16 (31% identical), DUSP12 (30% identical), DUSP22 (30% identical), DUSP1 (28% identical), DUSP4 (28% identical), DUSP8 (28% identical), DUSP13A (27% identical), DUSP2 (27% identical), and 19 more.
Diseases named in the same sentence as DUSP28 in open-access papers:
DUSP28 is named in the same sentence as 7 diseases in open-access papers, as found by Europe PMC text mining. Sharing a sentence is not in itself a finding about the gene and the disease. The quoted sentences say what the papers report.
pancreatic cancers (5 papers, 2015 to 2021). "A regulatory linkage between dual-specificity phosphatase 28 (DUSP28) and MUC5B/MUC16 was reported in pancreatic cancer cells by a study to elucidate the underlying mechanism by which DUSP28 promotes the development of pancreatic cancer." (PMID 32695780, 2020). "Recent reports indicated that DUSP28 is implicated in hepatocellular carcinoma progression and in migratory activity and drug resistance of pancreatic cancer cells, suggesting that this protein may be deeply involved in oncogenesis and could be a putative therapeutic target in some cancers." (PMID 29121083, 2017). "The present findings demonstrate that PDGF-A signaling pathway has critical roles in pancreatic cancer, and that its expression is regulated by functional DUSP28 at the mRNA and protein levels." (PMID 28986588, 2017). "We have reported that dual specificity phosphatase 28 (DUSP28) has a critical role of chemo-resistance and migration in pancreatic cancers." (PMID 28986588, 2017). "To demonstrate the role of DUSP28 expression to exogenous PDGF-A treatment in human pancreatic cancer, we examined the viability, migration, and invasion activities of pancreatic cancer cells following regulation of DUSP28 expression." (PMID 28986588, 2017). "These works will be worthwhile because of recent reports indicating DUSP28’s involvement in hepatocellular and pancreatic cancers." (PMID 29121083, 2017). "Enhanced DUSP28 sensitized pancreatic cancer cells to exogenous PDGF-A treatment in migration, invasion, and proliferation." (PMID 28986588, 2017). "In this study, we explored the unique role of DUSP28 in pancreatic cancer malignancy by inducing PDGF-A signals." (PMID 28986588, 2017). "Presently, we further investigated the functional correlation between DUSP28 and specific growth factors as natural cues to aggravate the malignancy of pancreatic cancers." (PMID 28986588, 2017). "We also confirmed that human pancreatic cancer cell lines have relatively varied levels of DUSP28 mRNA and protein, compared with human kidney 293T cells." (PMID 26212664, 2015). "We also showed that drug sensitivity was differently affected by DUSP28 expression levels in human pancreatic cancer in vivo." (PMID 26212664, 2015). "Downregulation of DUSP28 rendered cells sensitive to anti-cancer drugs again, through the caspase-3 apoptotic pathway, and it also decreased the migration activity of pancreatic cancer cells." (PMID 26212664, 2015). "Drugs currently used in clinical trials – gemcitabine and doxorubicin – were tested in a dose-dependent manner (0, 1, 10, 100, 1000 nM) to treat seven different human pancreatic cancer cells to assess the role of DUSP28 in drug resistance." (PMID 26212664, 2015). "The DUSP28 expression profile was obtained using the public microarray database GEO of human pancreatic cancer samples." (PMID 26212664, 2015). "We found that DUSP28 was highly expressed in several human pancreatic cancer cell lines that showed resistance to anti-cancer drugs." (PMID 26212664, 2015). "Our research provides further insight to control the malignancy involving DUSP28 as atypical positive feedback signaling and offers the possibility of DUSP28 as a new biomarker for pancreatic cancers." (PMID 26212664, 2015). "In this report, we demonstrated that pancreatic cancers show relatively high expression of DUSP28 versus normal pancreatic samples using the public microarray database GEO." (PMID 26212664, 2015). "In the present study, we investigated the role of dual specificity phosphatase 28 (DUSP28) in relation to anti-cancer drug sensitivity and migratory activity in human pancreatic cancer cells for the first time." (PMID 26212664, 2015). "The migration activities were also assessed in human pancreatic cancer cells with enhanced DUSP28 expression." (PMID 26212664, 2015).
pancreatic cancers (continued). "Together, these results indicate that DUSP28 plays specialized roles in chemo-resistance and migration in human pancreatic cancer cells via the ERK1/2 pathway." (PMID 26212664, 2015). "We investigated the DUSP28 expression levels in various human pancreatic cancer cell lines by Western blotting and quantitative real-time PCR." (PMID 26212664, 2015). "Analysis using Universal exPress Codes (UPCs) with the GEO database showed significantly higher DUSP28 mRNA expression in pancreatic cancers." (PMID 26212664, 2015). "Co-treatment with DUSP28 siRNA transfection and anti-cancer drugs in pancreatic cancer cells resulted in the typical morphology of apoptotic cell death." (PMID 26212664, 2015). "In the present study, we report the functional role of DUSP28 in pancreatic cancers for the first time." (PMID 26212664, 2015). "Our novel results demonstrate that DUSP28 plays a pivotal role in pancreatic cancer malignancy, suggesting that targeting DUSP28 might be a smart strategy for blocking pancreatic cancer." (PMID 28986588, 2017). "In summary, our results unveil the mechanisms underlying autonomous malignancy induced by natural cues in pancreatic cancers and suggest that DUSP28, an executor of a unique autocrine loop, could be a target molecule to inhibit pancreatic cancer malignancy." (PMID 28986588, 2017). "Here, we further clarify the function of DUSP28 in pancreatic cancers." (PMID 28986588, 2017). "This is the first report to our knowledge in that targeting DUSP28 might be a promising new therapeutic approach to inhibit the malignant pancreatic cancers." (PMID 28986588, 2017). "In addition, we investigated the roles of DUSP28 in the pancreatic cancer migratory characteristics using morphological changes and Western blot analysis." (PMID 28986588, 2017). "DUSP28 is one of the DUSP subfamily members that is known to be implicated in the progression of hepatocellular and pancreatic cancers, and its biological functions and enzymatic characteristics are mostly unknown." (PMID 29121083, 2017). "Our results demonstrate that DUSP28 plays a key role in the drug-resistance and migratory activity in human pancreatic cancer cells through the ERK pathway, suggesting that targeting DUSP28 might be a challenging strategy for patients with pancreatic cancer." (PMID 26212664, 2015). "Additionally, we showed that drug sensitivity was demarcated by basal expression patterns of DUSP28 in human pancreatic cancer cell lines." (PMID 26212664, 2015). "The convenient detection of a soluble form of DUSP28 might be a potential biomarker for pancreatic cancers." (PMID 26212664, 2015). "Pancreatic cancers expressed significantly more DUSP28 mRNA than the normal pancreatic samples." (PMID 26212664, 2015). "However, more research is required to reveal the specific conditions and mechanism involved in the release of DUSP28 from pancreatic cancers." (PMID 26212664, 2015). "Knockdown of DUSP28 re-sensitized cells to anti-cancer drugs even at sublethal doses by inducing an apoptotic pathway and significantly reduced migration in DUSP28-positive human pancreatic cancer cell lines." (PMID 26212664, 2015). "This phenotype suggested that DUSP28 might be a key molecule to regulate chemo-resistance and micro-metastasis in pancreatic cancers." (PMID 26212664, 2015). "Our results establish novel insight into DUSP28 and PDGF-A related autonomous signaling pathway in pancreatic cancer." (PMID 28986588, 2017). "To confirm the involvement of DUSP28 expression in PDGF-A induction, we analyzed the pancreatic cancer GEO public microarray database." (PMID 28986588, 2017). "Most notably, DUSP28 and PDGF-A were shown to form a unique autocrine loop that specifically affects the pancreatic cancer malignancy in vitro and in vivo through acquired intracellular signaling as self-sufficient armament modules." (PMID 28986588, 2017).
pancreatic cancers (continued). "The correlation between DUSP28 expression and various anti-cancer drugs was first examined using the CCLE database to investigate the role of DUSP28 in human pancreatic cancers." (PMID 26212664, 2015). "Moreover, dual-specificity phosphatase 28 (DUSP28) regulates chemo-resistance and migration in pancreatic cancers." (PMID 34858977, 2021). "Furthermore, DUSP28 and PDGF-A form a unique autocrine loop that specifically affected the pancreatic cancer malignancy in vitro and in vivo through acquired intracellular signaling." (PMID 28986588, 2017). "To investigate the functional roles of DUSP28 in drug resistance in vivo, we prepared DUSP28-positive and -negative pancreatic cancer models using Panc-1 and SNU-213 cells, respectively." (PMID 26212664, 2015). "However, there is no previous report about the cellular functions of DUSP28 in malignant pancreatic cancers features." (PMID 26212664, 2015). "Furthermore, transient overexpression of DUSP28 conferred chemoresistance to DUSP28-negative pancreatic cancer cells, including cell migration activity, via the ERK1/2 signaling pathway." (PMID 26212664, 2015). "Collectively, these results indicated that DUSP28 is a key molecule responsible for the chemo-resistance and migratory activity, through the ERK1/2 signaling pathway, and targeting DUSP28 with conventional chemotherapy might be an effective strategy for treatment of pancreatic cancers." (PMID 26212664, 2015).
inflammatory bowel disease (1 paper, 2026). A spectrum of small and large bowel inflammatory diseases of unknown etiology. "Additionally, decreased levels of DUSP2, DUSP11, DUSP22, and DUSP28 are associated with human inflammatory bowel diseases." (PMID 42087139, 2026).
liver cancer (1 paper, 2022). An epithelial or non-epithelial malignant neoplasm that arises from the liver. "Overall, our results showed that the four specific genes, TIPIN, RBM15B, DUSP28, and TRIM31, were likely prognostic biomarkers of liver cancer, and TIPIN might conspicuously accelerate the process of hepatocarcinogenesis." (PMID 35082931, 2022).
cancer (2 papers, 2015 to 2017). A tumor composed of atypical neoplastic, often pleomorphic cells that invade other tissues. "If DUSP28 only upregulates functionally soluble PDGF-A expression levels, the exogenous PDGF-A treatment should complement the anti-cancer effects of si-DUSP28 transfection." (PMID 28986588, 2017). "In the present study, remarkable anti-cancer effects of targeting DUSP28 were firstly observed in vivo models through the convincing inhibition of intracellular signaling." (PMID 28986588, 2017). "Overexpression of DUSP28 decreased anti-cancer drug-sensitivity and enhanced cellular migration via the ERK1/2 pathway in DUSP28-negative cell lines." (PMID 26212664, 2015). "Of interest, remarkable anti-cancer effects of targeting DUSP28 were observed in vivo models." (PMID 28986588, 2017). "We next tested whether reduction of DUSP28 expression by siRNA transfection could re-acquire sensitivity to the anti-cancer drugs gemcitabine and doxorubicin." (PMID 26212664, 2015). "There was a strong negative correlation between DUSP28 expression and various anti-cancer drugs, according to the CCLE data base." (PMID 26212664, 2015).
tumor (1 paper, 2017). "Tumor shapes of sh-DUSP28 tumor models (long/short axis) were close to 1 compared to the control group expressing DUSP28, indicating that DUSP28 expressed tumors seem to have longish characteristic compared to DUSP28 reduced tumors." (PMID 28986588, 2017). "Furthermore, targeting DUSP28 inhibited the tumor growth and migratory features through the blockade of PDGF-A expression and intracellular signaling in vivo." (PMID 28986588, 2017).
DUSP28 also shares sentences with these, for which no sentence is quoted: adenocarcinoma of the pancreas (1 paper); ductal-adenocarcinoma (1).